CRYGB (crystallin gamma B)
Description:
Crystallins are the dominant structural components of the vertebrate eye lens.
Synonyms: CRYG2; CTRCT39
Tractability: No criterion of Open Targets' tractability assessment is met for any kind of drug.
Gene: Protein-coding gene on chromosome 2 (208,142,573 to 208,146,158, reverse strand). Ensembl gene ENSG00000182187.
Subcellular location (Human Protein Atlas): Cytosol; Vesicles
Gene Ontology:
Molecular function: protein binding; structural constituent of eye lens
Biological process: lens development in camera-type eye; visual perception
Cellular component: cytoplasm; nucleus
Genetic constraint (gnomAD): Loss-of-function variants: 14 observed, 16.76 expected, observed/expected ratio (o/e) 0.84, 90% interval 0.55 to 1.3. The upper end of that interval is the gene's LOEUF score, 1.3, which puts it in group 5 of 6, group 1 being the genes least tolerant of losing a copy. Missense variants: 179 observed, 156.58 expected, observed/expected ratio (o/e) 1.14, 90% interval 1.01 to 1.29. Synonymous variants: 54 observed, 52.66 expected, observed/expected ratio (o/e) 1.03, 90% interval 0.82 to 1.29.
Homologues: Orthologues: chimpanzee CRYGB (99% identical), macaque CRYGB (96% identical), mouse Crygb (83% identical). Paralogues in human: CRYGC (79% identical), CRYGA (74% identical), CRYGD (72% identical), CRYGS (54% identical), CRYBA4 (35% identical), CRYBA1 (34% identical), CRYBG1 (33% identical), CRYBB1 (33% identical), CRYBB3 (32% identical), CRYBA2 (31% identical), CRYBB2 (31% identical), CRYBG2 (30% identical), and 2 more.
Diseases named in the same sentence as CRYGB in open-access papers:
CRYGB is named in the same sentence as 5 diseases in open-access papers, as found by Europe PMC text mining. Sharing a sentence is not in itself a finding about the gene and the disease. The quoted sentences say what the papers report.
cataract (3 papers, 2009 to 2013). Partial or complete opacity of the crystalline lens of one or both eyes that decreases visual acuity and eventually results in blindness. "We also observed novel sequence variations in the promoter region of CRYGB gene of pediatric cataract patients, which affected the putative TF binding sites in in silico analysis." (PMID 26317022, 2013). "This study is the first to report complex heterogeneous mutations in the CRYGB gene resulting in ADCC with three distinct phenotypes (lamellar, anterior polar, and complete cataracts) in the same family." (PMID 23288985, 2012). "Two novel heterozygous mutations in the crystallin gamma B (CRYGB) gene that cause autosomal congenital lamellar, anterior polar, and complete cataracts were detected in this study." (PMID 23288985, 2012).
Coronary Heart Disease (1 paper, 2023). "CRYGB has been identified as a differentially expressed gene in Coronary Heart Disease." (PMID 37098010, 2023).
type 1 diabetes (1 paper, 2021). "Fine-mapping of all the suggestive loci with gene burden tests using WES analysis revealed CRYGB and RELL1 to be potentially associated with the phenotype in individuals with type 1 diabetes." (PMID 33947878, 2021).
tumor (1 paper, 2023). "Four genes (UGT2B17, SST, CRYGB, and THRSP) were downregulated in tumor samples, whereas eighty genes were increased." (PMID 36785673, 2023).
CRYGB also shares sentences with these, for which no sentence is quoted: autosomal dominant congenital cataracts (2 papers).